STAT3 (signal transducer and activator of transcription 3)
Diseases named in the same sentence as STAT3 in open-access papers (continued):
Sharing a sentence is not in itself a finding about the gene and the disease.
inflammation (62 papers, 2010 to 2026). Aberrant reaction of the microcirculation characterized by movement of fluid and leukocytes from the blood into extravascular tissues. "Accordingly, several studies have indicated that JAK1/STAT3 is associated with pulmonary inflammation." (PMID 36698809, 2022). "Intriguingly, STAT3 deficiency can largely abrogates the effect of AMPK during LPS-induced pulmonary inflammation." (PMID 32210977, 2020). "Phospho-JAK2/STAT3 level were downregulated in FNDC5 OE mice, suggesting that the protective role of FNDC5 in cardiac inflammation are associated with JAK2/STAT3 pathway inhibition." (PMID 30940158, 2019). "We demonstrated that persistent activation of the Stat3 pathway in lung epithelial cells directly caused pulmonary inflammation and bronchioalveolar adenocarcinoma, supporting the concept that Stat3 is a pro-inflammatory molecule and oncogene." (PMID 22864832, 2012). "We established that IL-6 administration at the start of resuscitation is capable of completely reversing liver inflammation and is associated with increased Stat3 activation." (PMID 21738667, 2011). "All these findings were consistent to the effects of iPSC-MSCs on the neutrophilic airway inflammation and Th17 level, which collectively suggested that iPSC-MSCs were effective in the steroid-resistant neutrophilic airway inflammation and p-STAT3 was the underlying pathway involved." (PMID 29793557, 2018). "IL-6/STAT3 pathway has been implicated in renal inflammation and oxidative stress." (PMID 28367225, 2017). "During chronic intestinal inflammation, elevated IL-6 upregulates STAT3 activity in G-MDSCs via the IL-6R/JAK/STAT3 pathway, thereby increasing miR-93-5p transcription and subsequent enrichment in G-MDSC exosomes." (PMID 41346579, 2025). "PKM2 promotes Th17 cell differentiation and autoimmune inflammation by fine-tuning STAT3 activation." (PMID 38674024, 2024). "After acute or chronic systemic inflammation, the JAK2/STAT3 pathway is closely associated with regeneration of the heart, lung, liver, and kidney tissues in lipopolysaccharide (LPS)-induced mice." (PMID 37650558, 2023). "In liver inflammation, Cyr61 facilitated the expansion of HLA-DR−/lowCD33+CD11b+ myeloid-derived suppressor cells (MDSCs) via αmβ2/STAT3 signal and Cyr61/GM-CSF-induced MDSCs inhibited T-cell proliferation significantly." (PMID 31824953, 2019). "Kahweol has also been reported to protect against liver inflammation by downregulating the expressions of LPS-stimulated phospho-nuclear factor kappa B (NFkB) and signal transducer and activator of transcription 3 (STAT-3) expression." (PMID 30613574, 2018). "Preclinical studies using murine models demonstrated that cardiomyocyte-specific modulation of STAT3 activity can attenuate myocardial inflammation and improve cardiac output, with ginsenoside-Rc and other compounds showing promising effects via the STAT3/FoxO3a/SIRT1 axis." (PMID 40839200, 2025). "Studies have shown that drugs can reduce the levels of IL-6 and IL-1β by inhibiting STAT3 expression, thereby ameliorating liver inflammation; targeting the STAT3 signaling pathway is considered an attractive therapeutic strategy for the development of anti-inflammatory drugs." (PMID 37165407, 2023). "Further molecular analysis revealed that both pulmonary inflammation and PF were associated with increased transforming growth factor-β1 (TGF-β1), Janus activated kinase 2 (JAK2), and signal transducer and activator 3(STAT3) expression in the lung tissues of model rats." (PMID 35120332, 2022). "In this study, STAT3 activation may be related to excessive inflammatory response in the process of LPS induced cardiac inflammation and early stage of apoptosis, while STAT3 returned to normal level with the EA preconditioning." (PMID 36160853, 2022).
inflammation (continued). "Therefore, we have carried out studies to address the effect of GBE on simultaneously improving the depressive behaviors of MI rats, by relieving brain inflammation via transcription 3 (STAT3) pathway." (PMID 35677735, 2022). "Moreover, we found that STAT3 signaling was the potential pathway involved in the immunoregulatory functions of iPSC-MSCs on neutrophilic airway inflammation." (PMID 29793557, 2018). "Thus, pharmacological inhibition of Stat3 using GQ-ODN in rats subjected to T/HS and resuscitated with IL-6 completely blocked IL-6-mediated Stat3 activation and IL-6-mediated prevention of liver inflammation." (PMID 21738667, 2011). "In a CLP septic mouse model, RvD1 promoted the resolution of inflammation by upregulating SIRT1 expression and inhibiting the activation of STAT3, ERK, p38, and NF-κB in lung tissue, thereby reducing the severity of pulmonary inflammation." (PMID 40799817, 2025). "β-carotene in White Lablab modulates macrophage polarization and activates the JAK2/STAT3 and JNK/p38 MAPK signaling pathways to attenuate lipopolysaccharide-induced intestinal inflammation in rats." (PMID 36188567, 2022). "As a well-known anti-inflammatory cytokine, IL-10 can activate signal transducer and activator of transcription 3 (STAT3) in Kuppfer cells and regulate liver inflammation." (PMID 34124102, 2021). "Hypoxia stimulates reactive oxygen species (ROS) production and calcium release, activating inflammatory pathways (e.g., AP-1, STAT3, and MAPK) and increasing cytokines, such as IL-6, TNF-α, and IL-1, thereby exacerbating airway inflammation and lung ischemia–reperfusion injury." (PMID 41408473, 2025). "It is worth mentioning that mTOR was found to be able to activate NF-κB and signal transducer and activator of transcription 3 (STAT3) through the formation of immunoproteasomes, both of which play a significant role in the pathogenesis of cardiac inflammation and fibrosis." (PMID 40867548, 2025). "Emerging data on activation and function of STAT3 and SOCS3 in the lung during acute inflammation suggest that these molecules may regulate pulmonary inflammation, and they have specifically been implicated in allergic airway inflammation." (PMID 20826374, 2010). "In this study, we tested the hypothesis that targeted deletion of Il10 in mice would enhance O3-induced pulmonary inflammation via modulation of expression of inflammatory mediators CD86 and MIP-2 and nuclear transcription factors NF-κB and STAT3." (PMID 20826374, 2010). "Therefore, EED mediated PRC2 activation is involved in the regulation of cisplatin‐induced renal inflammation in AKI mice, and its mechanism may be related to the activation of STAT3 and NF‐κB signaling pathways." (PMID 35734954, 2022). "We further identified that the level of p-STAT3 was significantly decreased after the administration of iPSC-MSCs (n = 6) but not DEX (n = 6), suggesting that iPSC-MSCs may inhibit the differentiation of Th17 cells in this model of neutrophilic airway inflammation via downregulating p-STAT3 level." (PMID 29793557, 2018).
colorectal (50 papers, 2008 to 2026). "Activation of the STAT3 signaling pathway is associated with colorectal carcinogenesis and progression." (PMID 33996591, 2021). "Comparisons of RNAseq findings between HCT116- and HT29-derived tumorspheres revealed that HSPA5 were mediated by the STAT3-miR-30a-5p axis, which is overexpressed in colorectal tumorspheres associating to anti-apoptosis." (PMID 33023006, 2020). "Evidence consistently demonstrated that redox-sensitive pathways-including NF-κB, NRF2, and IL-6/JAK/STAT3-drive colorectal carcinogenesis by promoting genomic instability, immune evasion, angiogenesis, and therapy resistance." (PMID 41900943, 2026). "Our prior work demonstrated that MDSCs stimulate Foxp3+ Treg proliferation via phosphorylation of the Stat3 pathway, thereby promoting colorectal carcinogenesis." (PMID 40969768, 2025). "STAT3 in gonadal cells plays an anti-inflammatory role as well as a leading role in alcoholic liver injury." (PMID 37795374, 2023). "We found that MET, EGFR and phosphorylated STAT3 proteins were decreased after LOC389641 knockdown in human lung AD cell lines." (PMID 33318313, 2020). "It has been recently shown that the activity of pro-survival factors downstream of CDC42, such as PAK1 is increased in CDC42-driven colorectal tumorigenesis and these cascade pathways can regulate transcription through transcription factors like NFκB and STAT3." (PMID 28460460, 2017). "Another study revealed that the piR-54265/PIWIL2 complex could recruit STAT3 and P-SRC via the PAZ domain of PIWIL2, form the PIWIL2/STAT3/P-SRC complex, promote STAT3 phosphorylation and signaling pathway activation, and finally contribute to colorectal tumorigenesis." (PMID 34118972, 2021). "Notably, some studies have indicated that upregulation of IL-6/JAK/STAT3 signaling is one of the most important pathways involving in colorectal tumorigenesis and plays a pivotal role in the whole developmental processes, including initiation, development and formation in CRC." (PMID 28591704, 2017). "Several studies have proposed that STAT3 signaling may be involved in colorectal carcinogenesis." (PMID 26474284, 2015). "In summary, the data presented here demonstrated that STAT3 and CD47 are two potential therapeutic targets for the treatment of OS lung metastases." (PMID 40529368, 2025). "Inflammation is regulated by a variety of cell signalling pathways, including nuclear factor κB (NF‐κB), mitogen‐activated protein kinase (MAPK) and signal transducer and activator of transcription 3 (STAT3), that play critical roles in colorectal tumorigenesis." (PMID 37341064, 2023). "Although further clinical investigations will be required, our data suggest that those lung AC patients harbouring KRAS mutations or a known smoking history (as a surrogate marker for KRAS mutations), may not respond to STAT3 inhibitors but may likely suffer severe adverse effects." (PMID 25734337, 2015).
bacterial infection (49 papers, 2013 to 2026). "All patients were phenotypically similar to the classical autosomal dominant form of HIES associated with heterozygous mutations of STAT3, characterized by craniosynostosis and dental anomalies together with recurrent bacterial infections." (PMID 38133879, 2023). "This is consistent with the literature: IL-6 and STAT3 activation are linked with T cell expression of IL-17 (Th17 cells), which are key for protection against fungal and extracellular bacterial infections." (PMID 38133879, 2023). "Increased transepidermal water loss (TEWL) measurements mediated via STAT3 signaling suggest a skin barrier defect, which may increase the risk of bacterial infections." (PMID 37874473, 2023). "The data suggest that rhinoviral infections facilitate bacterial infections of airway epithelial cells by a cascade consisting of Stat3 activation, IRF8 upregulation, downregulation of acid ceramidase activity, and reduced sphingosine levels." (PMID 41861994, 2026). "In fact, decreases in bacterial infection in STAT3 KO cells were greater than those measured in cells treated with C188-9." (PMID 41115066, 2025). "On the contrary, when p38MAPK (p38MAPKi) and STAT3 (STAT3i) were inhibited in senescent cells there was a significant decrease in bacterial infection, while ERK inhibition (ERKi) significantly increased intracellular bacterial survival." (PMID 34746026, 2021). "In leptin receptor-deficient mice, studies showed that STAT3, STAT5, and ERK pathways play a key role in host defence against bacterial infections and in leukocyte function." (PMID 33907162, 2021). "HMGB1 also has important protective function in the colonic epithelium, because colonocyte HMGB1 was found to be directly involved in the suppression of STAT3 activation and the protection of intestine from bacterial infection and injury." (PMID 33193406, 2020). "Particularly, the STAT3 pathway plays unique roles in inflammatory responses and bacterial infection." (PMID 33089914, 2020). "STAT3 plays key functions in bacterial infection and inflammatory diseases, whose activation renders host‐bacterial interactions, mainly by controlling bacterial growth and reducing apoptosis." (PMID 33089914, 2020). "STAT1 is largely restricted to mediating the effects of IFNs, animals that lack STAT1 are exquisitely sensitive to microbial infections; while STAT3 mediates the effects of IL-6 and other gp130 ligands, and regulates the host response to bacterial infection." (PMID 33361763, 2020). "For example, increased expression of BiP and other chaperones during acute-phase response in mice with bacterial infection was regulated by binding of Signal Transducer and Activator Of Transcription 3 (STAT3) directly to Gpr78 promoter." (PMID 30908491, 2019). "Interleukin 6 (IL-6), acting via the IL-6 receptor (IL6R) and signal transducer and activator of transcription-3 (STAT3), limits neutrophil recruitment once bacterial infections are resolved." (PMID 26813342, 2016). "We for the first time demonstrate that during bacterial infection, a Lyn–IL-6R–Ezrin complex negatively regulates the IL-6/STAT3 signaling pathway in murine AMs." (PMID 29263906, 2016). "Stat3 concerts the host response to bacterial infection by controlling bacterial growth and suppression of apoptosis to maintain intestinal epithelial barrier function." (PMID 25799189, 2015). "Our study collectively shows that epithelial Stat3 concerts the host response to bacterial infection by controlling bacterial growth and suppression of apoptosis to sustain intestinal epithelial barrier function." (PMID 25799189, 2015). "Since STAT3 is responsible for MCL-1 upregulation at 72 hpi and is vital for bacterial infection, we evaluated whether STAT3 activation is an essential component of apoptotic inhibition by E. chaffeensis." (PMID 41115066, 2025).
bacterial infection (continued). "Together, these data suggested that WTAP-mediated m6A modification is deeply involved in the regulation of bacterial infection and inflammatory response in both humans and mice and may accelerate inflammatory responses by enhancing the STAT3 signaling axis." (PMID 39007267, 2024). "Multi-omics alterations of Stat1 and Stat3 indicated their central role in the host immune response to P. aeruginosa infection, and their downstream molecules may be potential targets against bacterial infections and inflammatory diseases." (PMID 37643174, 2023). "However, evidence revealed that bacterial infection induced the differentiation of macrophages to the M2 phenotype by IL6/STAT3/c−MYC signaling." (PMID 38035341, 2023). "In addition, STAT3 is involved in regulating the body’s response to viral and bacterial infections since the interaction of IL-6 and IL-10 with their respective receptors triggers the phosphorylation process of STAT3." (PMID 35327350, 2022). "Reports showed that STAT3 is important for defense against bacterial infection." (PMID 35370674, 2022). "This phenomenon is probably because, usually, the level of procalcitonin increases in the presence of cytokines, caused by a bacterial infection (IL-1b, TNF-a, and IL-6), and its production is regulated by the signal transducer and activator of transcription 3 (STAT-3)." (PMID 34439009, 2021). "Indeed, it has been reported that TRAF6 mediates K63 ubiquitination via the SH2 domain of STAT3, which is an essential step for STAT3 phosphorylation in response to bacterial infections." (PMID 33717204, 2021). "Importantly, STAT3 activation has been noted to be crucial for inflammatory diseases and in bacterial infection as well as the outcome of Mtb infection, but the potentially involved molecules remain complicated and elusive." (PMID 33089914, 2020). "Hence, the IL-15R/STAT3/IL-10R pathway described here appears to be a unique driver of NK cell IL-10 production during bacterial infection." (PMID 31552035, 2019). "Bacterial infection increased the expression of STAT3, JNK/SAPK, p38, and NF-κB in primary NHKs." (PMID 29152103, 2017). "As IL-6 activates transcription factor STAT3 to initiate the expression of other inflammatory factors, we studied whether Lyn regulates STAT3 in AMs during bacterial infection." (PMID 29263906, 2016). "Bacterial infections have been shown to collaborate with Stat3 signaling pathway to induce CRC." (PMID 25706309, 2015). "SOCS1 and SOCS3 are target genes of STAT1 and STAT3, respectively, and are critical negative regulators of JAK-STAT signaling and thus maintain normal cytokine levels during viral or bacterial infections." (PMID 33968006, 2021). "In various bacterial infection models, IL-6 was reported to induce DLL-1 expression in monocytes through the activation of STAT3." (PMID 32635645, 2020). "For bacterial infection, we propose for the first time a dependency of DLL1 transcription on STAT3 that is activated through TLR-induced cytokines and autocrine cytokine receptor signaling." (PMID 30042932, 2018). "STAT3 signaling is evidently beneficial for a variety of intracellular pathogens by multiple mechanisms, and the significant effect of STAT3 inhibition on bacterial infection suggests E. chaffeensis is no exception." (PMID 41115066, 2025). "Microbial products and bacterial infections may stimulate disease progression in CTCL because both, strong activation of STAT-3 and high expression of IL-10, were identified as markers of poor response to treatment in CTCL." (PMID 35267632, 2022). "Together, the data suggest that in senescent cells, ERK activity is necessary for iNOS transcription while p38 MAPK and STAT3 are negative transcriptional regulators of iNOS and hence their further inhibition decreases bacterial infection." (PMID 34746026, 2021).
bacterial infection (continued). "Further, if the effect of p38 MAPK and STAT3 inhibition on iNOS is via enhanced p-ERK levels, then inhibiting p-ERK activation in p38MAPKi or STAT3i senescent cells should abrogate the increase in iNOS levels and its resultant effect on bacterial infection." (PMID 34746026, 2021). "Inactivation of GSK3β by Akt-induced phosphorylation may result in activation of transcription factors during bacterial infection, including AP-1, STAT-1, STAT-3, and NF-κB." (PMID 29755479, 2018). "STAT3 and STAT1 are known to be up-regulated in cases of bacterial infection." (PMID 26220188, 2015). "As the two inhibitors with their proposed effects on SMAD1/5/9 signaling showed neither an inhibitor effect nor altered STAT3 phosphorylation, other hepcidin inducing pathways may play a dominant role during bacterial infection." (PMID 34368018, 2021). "The two bacterial infections could be distinguished from IAV infection by weaker induction of type I and type II IFN signaling, but stronger enrichment of signaling pathways such as IL2_Stat5_signaling, IL6_STAT3 signaling, programmed cell death, and KRAS signaling (upregulated genes)." (PMID 39395995, 2024). "The contrasting effects of STAT3 inhibition seen between non-senescent and senescent cells highlight that signalling changes occur due to senescence and a particular phenotype, which in this study is the host cell response to bacterial infection, maybe differently regulated by the same molecule." (PMID 34746026, 2021).